BAZ1B (bromodomain adjacent to zinc finger domain 1B)
Description:
Atypical tyrosine-protein kinase that plays a central role in chromatin remodeling and acts as a transcription regulator. Involved in DNA damage response by phosphorylating 'Tyr-142' of histone H2AX (H2AXY142ph). H2AXY142ph plays a central role in DNA repair and acts as a mark that distinguishes between apoptotic and repair responses to genotoxic stress. Regulatory subunit of the ATP-dependent WICH-1 and WICH-5 ISWI chromatin remodeling complexes, which form ordered nucleosome arrays on chromatin and facilitate access to DNA during DNA-templated processes such as DNA replication, transcription, and repair. Both complexes regulate the spacing of nucleosomes along the chromatin and have the ability to slide mononucleosomes to the center of a DNA template. The WICH-1 ISWI chromatin remodeling complex has a lower ATP hydrolysis rate than the WICH-5 ISWI chromatin remodeling complex. The WICH-5 ISWI chromatin-remodeling complex regulates the transcription of various genes, has a role in RNA polymerase I transcription (By similarity). Within the B-WICH complex has a role in RNA polymerase III transcription. Mediates the recruitment of the WICH-5 ISWI chromatin remodeling complex to replication foci during DNA replication.
Synonyms: WBSCR10; WBSCR9; WSTF
Tractability: PROTAC: UniProt records ubiquitination sites on it; ubiquitination databases record sites on it; its protein half-life has been measured.
Target class: Enzyme; Transferase
Gene: Protein-coding gene on chromosome 7 (73,440,406 to 73,522,293, reverse strand). Ensembl gene ENSG00000009954.
Subcellular location: Nucleus
Subcellular location (Human Protein Atlas): Nucleoplasm
Pathways (Reactome):
DNA Repair: Recruitment and ATM-mediated phosphorylation of repair and signaling proteins at DNA double strand breaks
Gene expression (Transcription): B-WICH complex positively regulates rRNA expression
Gene Ontology:
Molecular function: histone H2AXY142 kinase activity; protein binding; protein tyrosine kinase activity; histone binding; histone kinase activity; zinc ion binding; non-membrane spanning protein tyrosine kinase activity
Biological process: chromatin remodeling; DNA damage response; negative regulation of mitotic chromosome condensation; positive regulation of transcription by RNA polymerase III; post-translational protein modification; positive regulation of transcription by RNA polymerase I; positive regulation of transcription by RNA polymerase II; regulation of transcription by RNA polymerase II
Cellular component: B-WICH complex; nuclear replication fork; nucleoplasm; nucleus; WICH complex; nucleolus; condensed chromosome; pericentric heterochromatin
Genetic constraint (gnomAD): Loss-of-function variants: 21 observed, 150.78 expected, observed/expected ratio (o/e) 0.14, 90% interval 0.098 to 0.2. The upper end of that interval is the gene's LOEUF score, 0.2, which puts it in group 1 of 6, group 1 being the genes least tolerant of losing a copy. Missense variants: 1,315 observed, 1,852.5 expected, observed/expected ratio (o/e) 0.71, 90% interval 0.68 to 0.74. Synonymous variants: 675 observed, 659.86 expected, observed/expected ratio (o/e) 1.02, 90% interval 0.96 to 1.09.
Homologues: Orthologues: chimpanzee BAZ1B (99% identical), macaque BAZ1B (98% identical), dog BAZ1B (96% identical), pig BAZ1B (95% identical), rabbit BAZ1B (92% identical), guinea pig BAZ1B (92% identical), rat Baz1b (92% identical), mouse Baz1b (91% identical), tropical clawed frog baz1b (68% identical), zebrafish baz1b (61% identical), Drosophila melanogaster tou (10% identical), Caenorhabditis elegans bet-2 (4% identical). Paralogues in human: BAZ2B (18% identical), BAZ1A (18% identical), BAZ2A (17% identical), BPTF (14% identical), BRD4 (7% identical), BRD3 (7% identical), BRD2 (7% identical), KAT2A (7% identical), KAT2B (7% identical), BRDT (6% identical), CECR2 (6% identical).
Diseases named in the same sentence as BAZ1B in open-access papers:
BAZ1B is named in the same sentence as 30 diseases in open-access papers, as found by Europe PMC text mining. Sharing a sentence is not in itself a finding about the gene and the disease. The quoted sentences say what the papers report.
Williams syndrome (14 papers, 2011 to 2026). "While deletion, including BAZ1B, is known to cause Williams syndrome, the mechanism between SUA or gout and BAZ1B variants remains to be elucidated." (PMID 33517564, 2021). "Pathogenic mutations in BAZ1B are frequently associated with Williams-Beuren syndrome, which is a neurodevelopmental disorder characterized by craniofacial dysmorphology, cardiovascular problems, renal abnormalities and musculoskeletal abnormalities." (PMID 32278351, 2020). "WSTF is encoded by BAZ1B, and is one of twenty-eight genes that are hemizygously deleted in the genetic disorder Williams-Beuren syndrome (WBS)." (PMID 24168170, 2013). "For example, the baz1b gene is strongly associated with Williams-Beuren syndrome." (PMID 35148331, 2022). "However, we report on two nominally significant SNPs in two genes that have been implicated in the cognitive and social phenotypes of Williams syndrome, BAZ1B and GTF2IRD1." (PMID 30008175, 2018). "Loss of the chromatin remodeler WSTF (BAZ1B), a gene deleted in Williams syndrome, causes reproducible, genome-scale reprogramming of chromatin states and transcript processing that links altered chromatin composition to misprocessed transcripts and aberrant signaling." (PMID 42258541, 2026). "The human BAZ1B gene is known to be deleted in the development disorder Williams syndrome." (PMID 23244533, 2012). "Studying rare events that result in atypical deletions sparing different genes in the Williams syndrome critical region (WSCR), as well as single gene knock out studies in mouse models, have suggested that GTF2IRD1 and BAZ1B play a role in the craniofacial abnormalities." (PMID 30008175, 2018).
breast carcinoma (10 papers, 2014 to 2025). "In breast cancer, BAZ1B acts as an activator of a CYP19A1 gene that encodes the enzyme aromatase and ERα genes." (PMID 34736517, 2021). "Moreover, BAZ1B possesses high frequency of mutation in cutaneous cancer and lung carcinoma as well as high frequency of copy numbers amplification in breast cancer, gastric cancer and etc.." (PMID 34736517, 2021). "Menin also complexes with the H3K79 histone methyltransferase DOT1L and the epigenetic reader protein BAZ1B in ER-positive luminal breast cancer cells." (PMID 39336822, 2024). "BAZ1B phosphorylation at serine 158 (Ser158) significantly contributes to breast cancer tumorigenesis." (PMID 34680936, 2021). "BAZ1B-K426ac levels are significantly associated with MOF levels and are high both in breast cancer cell lines and in patient tissues." (PMID 34680936, 2021). "When combined, these results show for the first time a functional interdependence between Dot1L and menin in estrogen-sensitive and AE-resistant breast cancer, and point to BAZ1B as a member of a Dot1L-menin regulatory network exploitable for devising new ways to treat endocrine-resistant BC." (PMID 35850772, 2022). "Treatment with the vitamin D analog EB1089 effectively inhibits aromatase-dependent growth of breast cancer cells by dissociating BAZ1B from the CYP19A1 promoter in a vitamin D receptor (VDR)-dependent manner, suggesting that BAZ1B is a potential drug target in breast cancer." (PMID 34736517, 2021). "We have fully validated the epigenetic screens in vivo and in vitro by analyzing four different hits and we have demonstrated that BAZ1B, BPTF, BRD4 and CHD4 are essential for breast cancer growth." (PMID 27779108, 2016). "Several BrD members, namely BRPF1, SMARCA4, BRD7, BRD9, BAZ1B, ATAD2 and BRD4 are significantly upregulated in basal breast cancer subtype (when compared to less aggressive luminal A and normal‐like subtype), which strongly mimics the results obtained for the mRNA‐SI." (PMID 35049055, 2022).
lung carcinoma (4 papers, 2020 to 2023). "Specifically, BAZ1B overexpression promotes proliferation, colony formation, migration, and invasion of lung cancer cells." (PMID 36674511, 2023). "In our previous report, we determined a positive correlation between BAZ1B expression and cancer stemness in several types of solid tumors, including breast and lung cancers." (PMID 36674511, 2023). "BAZ1B exerts oncogenic functions in breast, colorectal, and lung cancers." (PMID 36674511, 2023). "Furthermore, BAZ1B was reported in lung cancer as an oncoprotein, where its overexpression promotes proliferation, colony formation, migration, and invasion of lung cancer cells as well as tumor growth and invasion in mouse xenograft models." (PMID 34680936, 2021). "Thus, BAZ1B likely promotes metastasis in lung cancer via the induction of EMT." (PMID 34680936, 2021).
colon cancer (3 papers, 2016 to 2021). "Knocking down BAZ1B or treating cells with antibodies to BAZ1B reduced cell proliferation and oncogenic pathway activation, implicating BAZ1B as a target for KRASG12 colon cancer." (PMID 34680936, 2021).
gout (2 papers, 2021 to 2022). A condition characterized by painful swelling of the joints, which is caused by deposition of urate crystals. "This prompted us to examine the association between common variants of A1CF, BAZ1B and gout using clinically-defined Japanese gout patients through a candidate gene approach, and to meta-analyze it with our previous gout GWAS data." (PMID 33517564, 2021). "This study shows the first known association between SNPs of A1CF, BAZ1B and clinically-defined gout cases in Japanese." (PMID 33517564, 2021). "The association of A1CF variation and BAZ1B variation with HUA and gout has also been concerned recently." (PMID 35922835, 2022). "The present study showed, for the first time, an association between rs10821905 of A1CF as well as rs1178977 of BAZ1B and gout in a Japanese population." (PMID 33517564, 2021). "Replication studies revealed both SNPs to be significantly associated with gout (P = 0.0366, odds ratio [OR] with 95% confidence interval [CI]: 1.30 [1.02–1.68] for rs10821905 of A1CF, P = 6.49 × 10–3, OR with 95% CI: 1.29 [1.07–1.55] for rs1178977 of BAZ1B)." (PMID 33517564, 2021). "Meta-analysis also revealed a significant association with gout in both SNPs (Pmeta = 3.16 × 10–4, OR with 95% CI: 1.39 [1.17–1.66] for rs10821905 of A1CF, Pmeta = 7.28 × 10–5, OR with 95% CI 1.32 [1.15–1.51] for rs1178977 of BAZ1B)." (PMID 33517564, 2021). "Of these, rs10821905 of A1CF and rs1178977 of BAZ1B showed the greatest and the second greatest significant effect size for increasing SUA level in the Japanese population, but their association with gout is not clear." (PMID 33517564, 2021). "The A1CF variant still showed a significant association with gout in the presence of the dysfunctional variants of ABCG2 but was no longer significant without those variants, while the BAZ1B variant remained significant both with and without ABCG2 dysfunction." (PMID 33517564, 2021). "However, the BAZ1B variation has a significant correlation with gout with or without ABCG2 dysfunctional variation." (PMID 35922835, 2022).
breast tumor (1 paper, 2022). "Given the crucial role of chromatin accessibility and remodelers in endocrine resistance in BC, we characterized in detail the role of BAZ1B and the effects of its inhibition in the breast tumor subtype that express ERα." (PMID 35850772, 2022). "Of interst, luminal-like breast tumors characterized by high levels of BAZ1B exhibited a worst overall and relapse-free survival, reflecting the more aggressive phenotype of these tumors, generally refractory to AE therapies." (PMID 35850772, 2022).
duodenal obstruction (1 paper, 2026). Hindrance of the passage of luminal contents in the DUODENUM. "Our observation of duodenal obstruction (Case 1) and craniofacial dysmorphism (Case 11) provides clinical evidence supporting BAZ1B's role in neural crest cell migration and differentiation." (PMID 41494975, 2026).
gastric cancer (1 paper, 2021). A primary or metastatic malignant neoplasm involving the stomach. "Ras-ERK1/2 induces BAZ1B degradation by increasing MDM2 expression to downregulate H2AXY142ph, which promotes cell growth and metastasis in gastric cancer." (PMID 34736517, 2021).
glioma (1 paper, 2023). A benign or malignant brain and spinal cord tumor that arises from glial cells (astrocytes, oligodendrocytes, ependymal cells). "By reviewing previous studies, we found that CASP2, NCAPG2, BAZ1B, and ZNF800, the genes most positively related to NUP205, were reported as carcinogenic genes in cancer, especially CASP2, NCAPG2, and BAZ1B, which were found to be carcinogenic genes in glioma." (PMID 37284202, 2023). "In our study, the NCAPG2 and BAZ1B genes were positively related to NUP205 and have been reported as oncogenes for glioma." (PMID 37284202, 2023).
hypothyroidism (1 paper, 2022). Abnormally low levels of thyroid hormone. "Furthermore, a recent study suggested that through the PTEN-mediated pathway, the deletion of BAZ1B gene heterozygosity reduces both the viability and survival of thyroid cells, thereby causing hypothyroidism in patients with WBS." (PMID 35379245, 2022).
Infertility (1 paper, 2022). "Moreover, the BAZ1B gene is also involved in the development of sperm, and its deletion may be one of the influencing factors of infertility in WBS patients." (PMID 35379245, 2022).
osteoporosis (1 paper, 2024). A condition of reduced bone mass, with decreased cortical thickness and a decrease in the number and size of the trabeculae of cancellous bone (but normal chemical composition), resulting in increased fracture incidence. "At present, there are few literature reports on the role of BAZ1B in osteoporosis." (PMID 38650009, 2024). "Given the effect of STAT3 on bone homeostasis, we believe that BAZ1B may also play an important role in osteoporosis." (PMID 38650009, 2024). "Therefore, the relationship between BAZ1B and osteoporosis needs to be further explored." (PMID 38650009, 2024).
osteosarcoma (1 paper, 2025). A usually aggressive malignant bone-forming mesenchymal neoplasm, predominantly affecting adolescents and young adults. "Meanwhile, higher expression levels of SMARCB1, UBQLN2, ENY2, and BAZ1B was observed in high-grade osteosarcoma prechemotherapy biopsy samples than that of MSCs." (PMID 40989695, 2025).
prostate carcinoma (1 paper, 2020). A carcinoma that arises from epithelial cells of the prostate gland. "The inferred subset GRN from the PC3 prostate cancer cell line suggests several genes as suppressors of SDHB, such as PNKB, PWP1, PNP, HADH, HTATSF1, and BAZ1B, among which PWP1, HTATSF1, and BAZ1B are transcription regulators." (PMID 33168813, 2020).
retinoblastoma (1 paper, 2018). A malignant tumor that originates in the nuclear layer of the retina. "Stress response proteins that were identified to be hyperphosphorylated in retinoblastoma compared to control retina tissues included H2AFX, SIRT1, TNIK, WRNIP1, BAZ1B, and CDK1." (PMID 29914080, 2018).
thyroid (1 paper, 2021). "Recently, BAZ1B, which is deleted in WS, has been linked with the thyroid developmental defects observed in some subjects with WS." (PMID 33557156, 2021).
type 2 diabetes (1 paper, 2023). "BAZ1B encodes a protein involved in chromatin-dependent regulation of transcription, and it has been associated with plasma lipid profiles in Chinese patients with type 2 diabetes." (PMID 36904157, 2023).
cancer (11 papers, 2013 to 2025). A tumor composed of atypical neoplastic, often pleomorphic cells that invade other tissues. "The overexpression of MOF and/or BAZ1B as well as a mutant the acetylation-mimicking variant of BAZ1B all result in cancer cell proliferation and migration." (PMID 34680936, 2021). "The tyrosine kinase bromodomain adjacent to zinc finger domain 1B (BAZ1B/WSTF) is upregulated in multiple cancers to drive migration and proliferation." (PMID 40508066, 2025). "Molecularly, BAZ1B activates both PI3K/Akt and IL-6/STAT3 oncogenic signaling pathways, which were previously linked to cancer stemness." (PMID 36674511, 2023). "An oncogenic role of BAZ1B in cancers has been postulated via its phosphorylation and acetylation, where it has been proposed that its abnormal activity would favor cancer progression." (PMID 35850772, 2022). "Here, we provide a comprehensive review to summarize the many aspects of BAZ1B function including its recent link to cancer." (PMID 34680936, 2021). "Recent findings also attribute BAZ1B as playing a central role in maintaining the mitotic chromosome structure as well as involvement in complex traits such as cancer progression and even animal behavior." (PMID 34680936, 2021). "If BAZ1B phosphorylation leads to its misregulation where its normal activity is required, such as in replication and transcription, then its plausible that its abnormal function is in favor of cancer progression." (PMID 34680936, 2021). "Bromodomain Adjacent to Zinc finger domain 1B (BAZ1B), Bromodomain PHD finger Transcription Factor (BPTF), Bromodomain containing 4 (BRD4) and CHD4 are key components of various epigenetic complexes implicated in cancer growth, progression and/or metastasis formation." (PMID 27779108, 2016). "Therefore, BAZ1B might be concerned as a cancer stemness-promoting factor." (PMID 36674511, 2023). "BAZ1B (also known as WSTF, the component of the WICH complex) and BAZ2A (also known as TIP5, the component of the NRC complex) are relatively well-recognized in cancer-supporting programs." (PMID 36674511, 2023). "BAZ1B-K426ac is mediated by the acetyltransferase MOF (males-absent on the first protein), the dysregulation of which has been highlighted in many types of human cancer." (PMID 34680936, 2021). "The overexpression of BAZ1B, and therefore that of SMARCA5, could potentiate the function of TOP1 during DNA replication, affecting the response of cancer cells to TOP1 inhibitors and to other treatments affecting replication." (PMID 33802597, 2021).
tumor (7 papers, 2016 to 2022). "Finally, it is worth highlighting that SMARCA5, which is overexpressed in different tumor types, forms a chromatin-remodeling complex with bromodomain adjacent to zinc finger domain 1B (BAZ1B) that facilitates the access of TOP1 at the replication fork." (PMID 33802597, 2021). "The impact of BAZ1B on ERα activity in hormone-responsive BC cells suggested the hypothesis that this protein could be an exploitable target to disrupt ERα-mediated signaling also in AE-resistant BC models that recapitulate the endocrine therapy-resistant tumor phenotype." (PMID 35850772, 2022). "Regardless of a possible role for BAZ1B phosphorylation, the acetylation of BAZ1B has been reported to promote the expression of tumor-related genes, increase cell proliferation, and promote tumor formation." (PMID 34680936, 2021).
BAZ1B also shares sentences with these, for which no sentence is quoted: colorectal cancer (2 papers); neurodevelopmental disorder (2); Baraitser-Winter syndrome (1); genetic disorder (1); hearing loss (1); heart diseases (1); Hypercalcemia (1); Intellectual disability (1); mental disorder (1); migraine (1); Rett syndrome (1).